TSC2 (TSC complex subunit 2)
Diseases named in the same sentence as TSC2 in open-access papers (continued):
Sharing a sentence is not in itself a finding about the gene and the disease.
tumor (continued). "As FNIP1/2 and Tsc1 scaffold the tumor suppressors FLCN and Tsc2 to Hsp90, it follows that these co-chaperones may participate in the chaperoning of additional Hsp90-dependent tumor suppressor clients." (PMID 35883484, 2022). "To explore whether Ref-1 inhibition has potency to revert other TSC-associated disease features, we carried out cell migration/invasion and tumor growth assays in Tsc2−/− MEFs after APX3330 treatment." (PMID 36551683, 2022). "In addition to regulating mTORC1, AMPKα activation inhibits tumour cell growth by phosphorylating TSC2 on S1387, which in turn inhibits mTORC1 leading to autophagy activation." (PMID 35670018, 2022). "Our results indicate that unlike what was reported in the brain samples of Tsc2 cKO mice and in tumor cells and sera of patients with TSC2 mutations, the renal polyamine levels and polyamine biosynthesis are not significantly altered in Tsc1 KO vs. Wt mice." (PMID 36142537, 2022). "This is the first report of a rare tumour harbouring TSC2 and SETD2 variations." (PMID 36510186, 2022). "In this article, we first report a rare tumour that harbours TSC2 and SETD2 variations." (PMID 36510186, 2022). "It is noteworthy that one Tsc2-KO tumor completely regressed after anti–PD-1 antibody treatment." (PMID 35119931, 2022). "It has been suggested that TSC1/TSC2 epigenetic silencing might contribute to tumor formation in TSC and could explain cases where the second hit mutation in TSC1/TSC2 is not found." (PMID 34709498, 2022). "The two tumor suppressor genes TSC1 and TSC2 are associated with the onset of TSC." (PMID 35692821, 2022). "This could indicate a higher proliferation status of LEAD since TSC2 is a known tumor suppressor acting mainly by inhibiting mTOR signaling." (PMID 35743538, 2022). "Although most TSC tumors are composed largely of tumor cells with complete TSC1/TSC2 loss, TSC FAFs occur in the dermis with nontumor vascular, inflammatory, and other components." (PMID 35358092, 2022). "We evaluated the changes in tumor volume to measure the effect of everolimus on Tsc2+/- mice." (PMID 35814396, 2022). "It is important to note that studies have shown that, in Tsc2+/- mice, therapeutic intervention demonstrates reduction in tumor volumes, but the cessation of therapy results in recovery of tumor growth, highlighting the importance of prolonged treatment and monitoring." (PMID 35814396, 2022). "TSC1/TSC2-null fibroblasts are the core tumor cells in TSC FAFs." (PMID 35358092, 2022). "The TSC2 protein forms a complex and functions as a tumor suppressor by inhibiting mTORC1 kinase." (PMID 34880877, 2021). "GD3 CAR T cells inhibit Tsc2–/– tumor growth in immunodeficient mice." (PMID 34806651, 2021). "TSC is a monogenic disease, and tumor cells with biallelic TSC1 or TSC2 mutations generally do not develop further heritable changes in other genes." (PMID 34806651, 2021). "GD3 CAR T cells limit spontaneous tumor in aging Tsc2+/– mice." (PMID 34806651, 2021). "This in turn lead to the activation of a signal transduction starting from the insulin receptor substrate (IRS), involving the phosphoinositide 3-kinase (PI3K) and Akt (PKB, protein kinase B) and inactivating the TSC Complex Subunit 2 (TSC2), known as a tumor suppressor." (PMID 35008275, 2021). "Furthermore, there were two genes (FBXW7, RET) mutated exclusively in tumours and eight (BLM, GJB2, NOTCH2, NOTCH3, NTRK1, POLE, SOS1, TSC2) solely in metastases." (PMID 34572946, 2021). "Mutation of TSC2 and its leading activation of MTORC1 upregulates the proteasome, which may facilitate estrogen-enhanced survival of tumor cells." (PMID 33922083, 2021). "Greater significance was observed when Tsc2–/– tumor cells were used as targets." (PMID 34806651, 2021).
tumor (continued). "AMPK suppresses tumor survival through inhibition of mTOR by increasing the expression of p-TSC2, a tumor suppressor gene, and leads to the inactivation of AKT and lipopolysaccharide (LPS)-induced IL-6/JAK2/STAT3 signaling in triple-negative breast cancer (TNBC)." (PMID 31952344, 2020). "In patient 10, CCND1 and TSC2 amplification were identified only in tumour #1." (PMID 31929516, 2020). "In fact, mutations within the PC, PRICKLE2 and TSC2 genes have previously been associated with non-neurodegenerative diseases including diseases involved in energy deficiency, tumour formation and seizures." (PMID 32019516, 2020). "Our results showed that the p-S6 expression was weaker in the ZA group, indicating that ZA could decrease the p-S6 expression in the TSC2-null cell tumor." (PMID 32063747, 2020). "In addition, well-studied tumor suppressors, such as PTEN (an Akt inhibitor), tuberous sclerosis 1 (TSC1), and TSC2 (mTOR inhibitors), give signals to stimulate autophagy, showing that raised autophagy signaling results in tumor suppression." (PMID 32121322, 2020). "Eker rats, which carry a germ-line mutation in the tuberous sclerosis complex 2 (Tsc2) tumor suppressor gene, are susceptible to UFs and provide a suitable animal model for studying gene-environment interactions, especially as DES exposure increases the Tsc2 penetrance, tumor multiplicity and size." (PMID 32545544, 2020). "Other studies also reported mutations and gene variations either directly in immune system-related genes, such as PD-1, PD-L1, IDO, and VEGF, or in tumor suppressor genes such as TSC2 and VHL, along with transcriptional upregulation of oncogenic pathways in patients with HPD." (PMID 31683809, 2019). "In keeping with these results, loss of specific tumor suppressors, such as promyelocytic leukemia protein (PML) or tuberous sclerosis proteins 1 and 2 (TSC1 and TSC2), has been shown to promote HIF-1α expression through suppression of hypoxia-induced inhibition of mTOR." (PMID 31530290, 2019). "Previously, UL38 was found to bind and inhibit TSC2, a tumor suppressor that inhibits mTORC1." (PMID 30677091, 2019). "In contrast, somatic mutations in tumor-promoting genes (FGFR1, RAC1, AFF3, AFF4, TSC2) may be intuitively associated with unfavorable prognosis." (PMID 30662871, 2018). "Further experiments utilizing a FLCN construct harboring the germline mutation of this patient suggest that there may be some ability of FNIP1 and Tsc1 to compensate for one another in the chaperoning of the FLCN and Tsc2 tumor suppressors." (PMID 29774133, 2018). "The absence of both Tsc1 and Tsc2 protein expression in the tumor, however, suggests loss of Tsc1 is driving this neoplasm because Tsc2 is known to depend on Tsc1 for stability, but Tsc1 stability does not depend on the presence Tsc2." (PMID 29774133, 2018). "We observed that salinomycin as a single agent could markedly block tumour spheroid formation of Tsc2−/− MEFs in soft agar as well as TSC-patient derived AML cells that also lack Tsc2." (PMID 28415776, 2017). "These generally (seven of nine tumours) co-occurred with large aberrations to TSC1/TSC2 (large deletions or CN-LOH), suggesting certain genomes may be less structurally stable." (PMID 28643795, 2017). "These RNA signatures were shared by tumours regardless of TSC1/TSC2 mutational status or presence of second hits." (PMID 28643795, 2017). "Polycystin-1 and the TSC1/TSC2 tumor suppressor complex both act to suppress the activity of mTOR." (PMID 29479522, 2017). "Despite considerable heterogeneity, tumours with one or two truncating mutations in TSC2 showed reduced levels of TSC2 mRNA transcripts compared to non-TSC tissues (pair-wise Welch’s t-tests; FDR-adjusted P=0.01)." (PMID 28643795, 2017). "Furthermore, an elevated level of p-AKT was observed in tumor tissues derived from PDGFRα-overexpressing Tsc2−/− or Tsc1−/− MEFs as compared to the control tissues." (PMID 28903387, 2017).
tumor (continued). "Moreover, overexpression of PDGFRα accelerated cell proliferation and tumor growth of Tsc1- or Tsc2-null MEFs." (PMID 28903387, 2017). "The expression profiling study on PNETs found that down-regulation of PTEN or TSC2 correlated with tumor aggressiveness but as addressed by the authors, PTEN and TSC2 might not be independent prognostic biomarkers at multivariate analysis." (PMID 28526880, 2017). "Biallelic inactivation of TSC2 or TSC1 is believed to represent the driving event in these tumours." (PMID 29133867, 2017). "We compared rapamycin-treated Tsc1-/- and Tsc2-/- MEFs to non-treated cells, as loss of the tumor suppressor gene fully activates mTORC1 signaling in both cell types." (PMID 26872016, 2016). "While the GAP domain of TSC2 contains the tumor suppressor activity, studies indicate that TSC1/TSC2 function primarily as a protein complex, and that TSC1 is required for the stabilization of TSC2 and prevents TSC2 ubiquitination by HERC1 ubiquitin ligase and subsequent degradation." (PMID 27409169, 2016). "Sample S22 also had low tumor purity (~10%) but showed evidence of TSC2 LOH without somatic mutations." (PMID 27494029, 2016). "Similarly, in a murine model of TSC2-null tumours, rapamycin inhibited tumour growth but its withdrawal resulted in TSC2-null tumour regrowth together with a decreased survival." (PMID 26282580, 2015). "In our preclinical studies, therapeutic targeting of Rho GTPase in Tsc2-null cells, tumors and lung lesions induces cell apoptosis and prevents Tsc2-null tumor recurrence thus identifying simvastatin as a potential drug for diseases are associated with TSC2 deficiency." (PMID 25360538, 2014). "Loss of TSC2 leads to activation of MTOR and downstream signaling elements, causes endoplasmic reticulum (ER) stress, activates the unfolded protein response, and results in tumor development." (PMID 25469175, 2014). "By contrast, no tumor-inhibitory effect of atorvastatin was detectable on the development of murine TSC2-associated liver hemangiosarcomas." (PMID 25319454, 2014). "Although identical TSC1 or TSC2 mutations among tumor cells are not always observed in TSC-LAM and S-LAM patients, it is clear that LAM cells are mobile; markedly, LAM cells are able to infiltrate and repopulate healthy donor lungs following transplantation." (PMID 25505789, 2014). "TSC2 is a tumor suppressor and is able to stimulate specific GTPases." (PMID 25469175, 2014). "DMD may thus connect to the long bristles module and act upstream of Akt-TSC2 signalling in tumor and synapse biology." (PMID 24204314, 2013). "We asked whether TSC2 repression was sufficient and required for ISC differentiation downstream of N, and found that loss of TSC1/2 indeed rescued the tumor phenotype of NRNAi expressing ISCs (in both MARCM clones, and when driven by esg::Gal4)." (PMID 23144631, 2012). "The paradoxical increase in tumor size with reduced tumor SUVmax in the "Carb-free" group suggests the possibility of alternative energy sources besides glucose that were utilized by the Tsc2-/- tumor cells." (PMID 22018000, 2011). "A few oncogenes (e.g. phosphatidylinositol 3-kinase, activated AKT1) inhibit autophagy, while numerous tumor suppressors (e.g. BH3-only proteins, death-associated protein kinase-1, PTEN, tuberous sclerosic complex 1 and 2, TSC1 and TSC2 and LKB1/STK11) induce autophagy." (PMID 21191146, 2010). "Single agent asparaginase improves survival and reduces Tsc2-/- tumor growth." (PMID 20146790, 2010). "Interestingly, the A/J Tsc2+/- strain shows a significantly higher tumor burden at 5 months of age than the C57BL/6 Tsc2+/- strain at 12 months of age." (PMID 20146790, 2010).
tumor (continued). "AKT phosphorylates TSC2 to inhibit its tumor suppressor function and activate mTOR signaling." (PMID 20169078, 2010). "Single agent bevacizumab improves survival and reduces Tsc2-/- tumor growth." (PMID 20146790, 2010). "In this study, we sought to improve the Tsc2+/- mouse as a preclinical model for TSC tumor studies." (PMID 20146790, 2010). "AMPK activates the tumor suppressor function of TSC2, leading us to investigate whether AMPK was potentially mediating PC-1 activation of TSC2." (PMID 20169078, 2010). "AKT phosphorylation of TSC2 at S939 and S981 results in the binding of 14-3-3 proteins to TSC2, leading to the partitioning of TSC2 away from the membrane into the cytosol and inactivating this tumor suppressor." (PMID 20169078, 2010). "In prior preclinical studies, we used two TSC2 tumor models to demonstrate that while both the rapamycin analog, CCI-779, and IFN-g are effective in reducing tumor growth, rapamycin is more effective than CCI-779, and effective rapamycin doses are absorbed after topical administration." (PMID 19368729, 2009). "Within AMLs, both the smooth muscle and adipose components display loss of heterozygosity (LOH) at the TSC2 locus, demonstrating that both cell types are constituents of the tumor rather than stromal derivatives." (PMID 19593385, 2009). "A linkage between the LKB1 and the TSC2 tumor suppressors may account in part for the apparent opposite effects of AMPK activation on cell survival and cell-death." (PMID 18474106, 2008). "We set out to test the hypothesis that PPARγ ligands activate tuberous sclerosis complex-2 (TSC2), a tumor suppressor gene that inhibits mTOR signaling." (PMID 17597835, 2007). "Treatment with rapamycin was more effective in reducing tumor growth and improving survival in nude mice bearing Tsc2-/- tumors and also resulted in higher rapamycin levels in blood, brain, and kidney tissue than treatment with an equal milligram dose of CCI-779." (PMID 17986349, 2007). "Moreover, estrogen-promoted lung colonization of TSC2-deficient cells is dependent on neutrophils and there is a clustering of tumor-promoting neutrophils in the lungs of LAM patients (not in control patients)." (PMID 40600043, 2025). "On the other hand, SEGA patients may have two independent inactivating somatic mutations in TSC1 or TSC2, and thereby, both copies of the TSC1 or TSC2 gene are lost in the cells that form the tumor, but the mutations in other patients’ cells are absent." (PMID 39410026, 2024). "Their findings indicated that the tumor may demonstrate copy number amplification of chromosomes 16, 7, 13q, and 19p, as well as copy number deletion of Xp11.21 and 22q11.23, along with loss of heterozygosity of TSC1 and TSC2." (PMID 38892169, 2024). "Thus, TSC2 acts as a tumor suppressor to limit protein synthesis and cell growth." (PMID 38907105, 2024). "Additionally, we constructed a stable cell line with TSC2 knockdown, which is the classical model that leads to constitutively active mTOR, and found that the tumor suppressive effect of VC could be eliminated by the knockdown of TSC2." (PMID 36787291, 2023). "This may be due in part to the hostile tumor microenvironment, and to that end, creating CAR-T cells with a TSC2 SA mutation may help circumvent this limitation by improving effector function and long-term survival even in hypoxic and/or acidic microenvironments." (PMID 37788104, 2023). "Finally, therapies that selectively induce cytotoxicity in TSC1- or TSC2-null tumor cells could provide a targeted approach to eliminate TSC-associated tumors without harming normal cells." (PMID 38137462, 2023). "We speculate that the hypoxic signaling involved in angiogenesis and tumor growth becomes elevated in hypoxic TSC2-deficient tissue that is not dependent on mTORC1." (PMID 36551683, 2022). "The destruction of TSC1/TSC2 tumor suppressor function may contribute to the occurrence of tumor." (PMID 35572821, 2022).
tumor (continued). "Subsequently, autophagy cannot be induced adequately with numerous metabolic defects existing in Tsc2-/- MEFs and further suppression of autophagy may exhibit an inhibitory effect on tumor development, showing the paradoxical effect dependent on cellular metabolic status." (PMID 34609442, 2021). "The lack of primary tumor sample prevented us to determine the trunk mutations of this patient, whether bi-allelic TSC2 mutations were involved in tumorigenesis or dedifferentiation should be determined in other cohorts or functional assay." (PMID 34249677, 2021). "However, inhibition of uPA expression in TSC2-null tumor cells could not only reduce their invasive and mitogenic potentials but also increase their susceptibility to the pro-apoptotic agent simvastatin." (PMID 33072782, 2020). "Therefore, mutations in TSC2 may lead to unstable TSC2 and therefore led to the development of TSC tumours." (PMID 33273660, 2020). "Moreover, RSKs inhibit the tumor-suppressor TSC2 through phosphorylation at its residue Ser1798." (PMID 31920959, 2019). "Mutations in NF1, TSC2 or PTEN-encoding for key suppressor genes of this pathway, and altered expression of the mTOR pathway components, are common hallmarks of a great proportion of NETs, wherein these alterations seem to be directly related with tumour development and progression." (PMID 31443481, 2019). "To determine whether Tsc2-deficient cells are Vps34-dependent in vivo, we inoculated 2.5 × 106 Tsc2-deficient cells with downregulation of Vps34 (shPIK3C3) or shCTL subcutaneously into NOD/SCID/IL2gR deficient mice (n =10 mice/group) and monitored tumor growth." (PMID 30242175, 2018). "On the other hand, TSC2-deficient tumors with impaired eIF2αP displayed accelerated initiation by ~23 days compared to TSC2-deficient control tumors whereas the rates of tumor growth did not significantly differ between the two cell types (compare graphs e and h) (e and g)." (PMID 29449538, 2018). "In addition to merlin, CRL4 can also upregulate the mTOR pathway through promoting ubiquitination and degradation of tuberous sclerosis 2 (TSC2), a tumor suppressor, that forms a complex with TSC1 which can inhibit the mTOR signaling in a RheB-dependent manner." (PMID 26460955, 2015). "However, since inactivation of the Tsc2 and folliculin genes in mice have been associated with the development of renal tumours and mammalian target of rapamycin (mTOR) disregulation, we investigated the OTA-associated tumours for evidence of mTOR activation." (PMID 23105973, 2012). "The primary tumor showed few genomic alterations with a deletion of the PKD1 and TSC2 region on chromosome 16, a LOH of the 17p region, a deletion of chromosome 18, and a partial deletion of chromosome 19." (PMID 41416936, 2026). "PTEN is a strong tumor suppressor that uses its phosphatase activity to negatively regulate the AKT pathway and positively influence TSC2." (PMID 39901197, 2025). "Additionally, although canonical cell proliferation can be regulated by VPS34 through downregulating TSC2 and activating mTORC1, research also showed that VPS34 inhibition decreased micropinocytosis in TSC2-null cells and suppressed TSC2-deficient tumor growth in mice." (PMID 39821606, 2025). "Tumor TSC-null EV treated 621 – 101 spheres upregulate and downregulate 805 and 297 genes, respectively, relative to TSC2 EV treated spheres." (PMID 40166013, 2025). "The upregulation of OXPHOS genes and increase in ATP are likely mediated by increased expression and delivery of critical mitochondrial function regulator, Nrf276 by tumor TSC-null EV, compared to tumor TSC2 EV." (PMID 40166013, 2025).